ALK (ALK receptor tyrosine kinase)
Diseases named in the same sentence as ALK in open-access papers (continued):
Sharing a sentence is not in itself a finding about the gene and the disease.
thyroid cancer (continued). "In this context, treatment with ALK inhibitors in ALK-rearranged thyroid cancer patients showed promising results in terms of response rate and disease control." (PMID 35600349, 2022). "Detailed characterization of ALK-driven thyroid cancer has recently been described elsewhere, with infiltrative (FV)PTC as the most typical morphology." (PMID 33878728, 2021). "In this study, ALK targeted therapy with crizotinib and lorlatinib in a thyroid cancer patient harboring an EML4-ALK gene fusion v3, is illustrated." (PMID 33878728, 2021). "The anaplastic lymphoma kinase (ALK) fusion with striatin (STRN) was identified in patient derived thyroid cancer cells in 2014, which leads to continuous MAPK signaling through MEK activation." (PMID 34335481, 2021). "In thyroid cancers, ALK fusions, most frequently the STRN-ALK fusion, are detected in PTC and, with higher frequency, in PDTC and ATC." (PMID 32235612, 2020). "Mutations and gene rearrangements have also been reported in anaplastic lymphoma kinase (ALK) gene in thyroid cancer." (PMID 32751138, 2020). "Kinase fusions have been identified in distinct histological subtypes of thyroid cancer, including papillary thyroid cancer (PTC; RET, NTRK1/2/3), medullary thyroid cancer (ALK), and poorly differentiated thyroid cancer (RET, ALK)." (PMID 32292131, 2020). "ALK fusions are primarily seen in aggressive thyroid-cancer types, and they are known to activate MAPK and PI3K signaling pathways." (PMID 32751138, 2020). "Only one case of a thyroid cancer patient withALK fusion treated with an ALK inhibitor has been reported in the literature." (PMID 31583077, 2018). "Fourth, crizotinib was shown to suppress the growth of ALK+ thyroid cancer cells; however, this potential therapeutic benefit was produced from non-Met/ALK-targeting effects." (PMID 29143801, 2017). "We performed Sanger sequencing to detect BRAF V600E and TERT promoter mutations and both immunohistochemistry and fluorescence in situ hybridization to identify ALK rearrangement on 243 thyroid cancers." (PMID 26857243, 2016). "Mutations in the TERT promoter, ALK rearrangement, and the BRAF V600E mutation are associated with aggressive clinicopathologic features in thyroid cancers." (PMID 26857243, 2016). "One of the ALK rearrangements described involves the striatin (STRN) gene observed more commonly in thyroid cancers." (PMID 25276134, 2014). "We report here the subsequent identification of STRN gene as the ALK fusion partner and the screening via RT-PCR of a series of 75 thyroid carcinoma samples in order to test the presence of the STRN/ALK fusion." (PMID 24475247, 2014). "This case highlights the potential role of sequential ALK inhibition to overcome acquired resistance in ALK-rearranged TC and underscores the importance of comprehensive molecular profiling to guide personalized treatment strategies in rare aggressive thyroid cancers." (PMID 41878530, 2026). "RET and ALK fusions or high microsatellite instability are potential targets in thyroid cancer." (PMID 40844731, 2025). "Although ALK fusion represents <1% of thyroid carcinoma, it is more frequently seen in PDTC." (PMID 37510219, 2023). "There is no current FDA-approved treatment for ALK kinase fusion-related thyroid carcinomas; however, ALK inhibitors may be used for clinical trials or off-label treatment in advanced cases." (PMID 37510219, 2023).
thyroid cancer (continued). "ALK occurs rarely, with limited data suggesting the efficacy of ALK inhibitors in thyroid cancer." (PMID 36439495, 2022). "Finally, molecular events involving ALK have also been identified in aggressive thyroid cancers and neuroblastomas." (PMID 35233056, 2022). "Moreover, a high prevalence (16%) of poorly differentiated thyroid carcinomas has been observed in a series of ALK-fused thyroid cancers." (PMID 33543394, 2021). "This fusion could lead to constitutive activation of ALK kinase fusion via dimerization mediated by the coiled‐coil domain of STRN as proved in thyroid cancer both in vitro and in vivo." (PMID 34541785, 2021). "Anaplastic lymphoma kinase (ALK) gene translocations have been implicated as pathogenic events in a proportion of PTC (0–9%), PDTC (0–4%), and ATC (0–4%), with some reports indicating a greater prevalence in dedifferentiated thyroid cancers." (PMID 35008368, 2021). "This seems to fit the range of previously observed morphologies in ALK-driven thyroid cancer." (PMID 33878728, 2021). "However, a large cohort of 259 thyroid cancers only found ALK rearrangements to be more common in young females and diffuse sclerosing variant PTC, but ALK-fusion positive PTCs do not appear to behave more aggressively." (PMID 31835496, 2019). "Recently, ALK gene translocations were identified in patient-derived thyroid cancer cells." (PMID 29455653, 2018). "ALK gene rearrangements have recently been identified in thyroid cancer." (PMID 26857243, 2016). "Indeed, non-MET related effects of crizotinib were reported to contribute to the cell-cycle arrest and cytotoxicity observed in thyroid cancer cells and inhibition of other RTKs, independently of ALK expression and activity, was recently observed in RMS cells." (PMID 26445453, 2015). "Notably, thyroid cancers have the highest frequency of recurrent kinase fusions (63/498, 13%), and all fusion events including ALK, BRAF, MET, NTRK1, NTRK2, RAF1 and RET are mutually exclusive in this cancer type." (PMID 25204415, 2014). "In order to see if the STRN/ALK fusion transcript could be observed in other thyroid carcinomas we have performed RT-PCR screening on 75 thyroid tumors (50 malignant and 25 benign)." (PMID 24475247, 2014). "In undifferentiated anaplastic thyroid cancer, two novel point mutations, C3592T and G3602A, found in exon 23 of the ALK gene, with a prevalence of 11.11%, but found no mutations in the matched normal tissues or in well-differentiated thyroid cancers." (PMID 22654559, 2011). "Furthermore, a correlation was observed between ALK fusion and aggressive thyroid carcinoma." (PMID 39685621, 2024). "Most notably, ALK rearrangements occur in approximately 3–7% of NSCLCs, approximately 50% of all inflammatory myofibroblastic tumors (IMTs), 10% of Spitzoid neoplasms, as well as small percentages in colon cancer, thyroid cancer, and several other types of malignancies." (PMID 29455648, 2018). "ALK rearrangements are rare but actionable oncogenic drivers in thyroid cancer, particularly in aggressive histologies such as poorly differentiated thyroid carcinoma (PDTC), and evidence supporting sequential ALK inhibition in this setting is scarce." (PMID 41878530, 2026). "A subset of thyroid cancers is initiated by gene rearrangements involving receptor tyrosine kinase (RTK) genes, such as RET, ALK and NTRK (5–10%), that also activate the MAPK pathway." (PMID 41175860, 2025). "The next-generation IHC for BRAF V600E, RAS Q61R, pan-TRK, ALK, PTEN, and β-catenin has promising roles in the diagnosis and molecular classification of thyroid carcinomas." (PMID 40111709, 2025). "These exon usages were identical to the corresponding ALK fusions found in NSCLC and thyroid cancer." (PMID 38877018, 2024). "Fusion of ALK, which is rare in PTC, was found in thyroid carcinoma through RNA sequencing analysis." (PMID 39685621, 2024).
thyroid cancer (continued). "Currently, two non-selective HGFR TKIs have been approved: crizotinib (first approved in 2011) for ALK- and ROS1-positive NSCLC and cabozantinib (First approved in 2016) for thyroid cancer and kidney cancer." (PMID 37543570, 2023). "Evaluation of thyroid FNAs with the Unified Assay identified all fusion proteins described for thyroid cancer in TCGA, the most common fusion pair being PAX8-PPARg, with other common fusion partners including RET, NTRK1/3, ALK, and BRAF." (PMID 36675685, 2022). "Our findings corroborate that also in thyroid cancer with EML4-ALK v3, targeting ALK appears feasible." (PMID 33878728, 2021). "An additional development in the management of thyroid cancer which has been proven highly effective in preliminary clinical trials is the use of therapy aimed at targeting NTRK and ALK gene fusions." (PMID 32751138, 2020). "ALK-inhibitors are FDA-approved for solid tumors that harbor ALK fusions and a few patients with thyroid cancer have been included in the reported clinical trials and/or case reports, although no ALK-inhibitors are currently FDA-approved for DTC specifically." (PMID 36909304, 2023). "ALK translocations appear to be more frequent post-radiation, in female PTC patients, have been variably reported in the pediatric age group, and occur independently of other known driver molecular alterations in thyroid cancers." (PMID 35008368, 2021). "Additionally, new targets are now being explored in the field of thyroid cancer, such as MEK, ERBB2/HER2, ALK or SSTR in order to increase the therapeutic possibilities and offer the adequate directed treatment to the patients." (PMID 32668761, 2020). "The search of ALK rearrangements in thyroid cancers may be as important as in NSCLC and the efficiency of treatment by ALK inhibitors must be further evaluated." (PMID 24475247, 2014). "Because ALK inhibitors such as crizotinib, ceritinib, and alectinib are currently available and FDA approved for ALK-fusion positive NSCLC, patients with advanced ALK fusion-positive thyroid cancer may respond to ALK inhibitors." (PMID 31835496, 2019). "In our study, ALK rearrangement was not identified in any thyroid cancers." (PMID 26857243, 2016). "None of the 243 thyroid cancers had positive ALK immunohistochemistry or ALK break apart FISH." (PMID 26857243, 2016). "Although there are several ALK inhibitors that are FDA approved for lung cancer, none have been approved for thyroid cancer." (PMID 34335481, 2021).
diffuse large B-cell lymphoma (62 papers, 2007 to 2026). "ALK-positive ( +) large B cell lymphoma (ALK + LBCL) is a rare distinct subtype of diffuse large B cell lymphoma presenting with high stage and aggressive behavior." (PMID 38573563, 2024). "DLBCL, diffuse large B-cell lymphoma; MALT, mucosa-associated lymphoid tissue; ALK, anaplastic lymphoma kinase positive." (PMID 35784957, 2022). "ALK-positive LBCL is an aggressive subtype of diffuse large B cell lymphoma as more than 76% of the documented cases were in stage III-IV." (PMID 28665943, 2017). "Anaplastic lymphoma kinase (ALK)-positive diffuse large B-cell lymphoma (ALK+ DLBCL) is a rare novel subtype of DLBCL that was recognized as a separate entity in the 2008 World Health Organization (WHO) classification of lymphoid neoplasms." (PMID 25009592, 2014). "This novel ALK-TOPK pathway may also function in other ALK-positive cancers, such as diffuse large B-cell lymphoma or inflammatory breast cancer, and TOPK could be a favorable target for the treatment of ALK-positive cancers." (PMID 36167821, 2022). "Diffuse large B cell lymphomas (DLBCL) harbouring ALK fusion proteins were first described in 1997." (PMID 21494621, 2011). "Anaplastic lymphoma kinase (ALK) is a tyrosine kinase receptor found activated due to different genetic alterations (chromosomal translocations, substitution mutations and gene amplification) in many cancers including anaplastic large-cell lymphomas (ALCL) and diffuse large B-cell lymphomas." (PMID 36909156, 2023). "Indeed, today there is a wide consensus that lymphomas with an anaplastic morphology, characterized by a B cell phenotype and ALK negativity, represent a subtype of Diffuse Large B-cell Lymphoma (DLBCL)." (PMID 41283513, 2025). "ALK+ LBCL is a type of rare CD20-negative invasive non-Hodgkin lymphoma, accounting for less than 1% of diffuse large B-cell lymphoma (DLBCL) cases." (PMID 39906668, 2024). "This was followed in-tandem by a phase I study in adults with ALK-positive NHL (ALK-positive ALCL: n = 9, ALK-positive diffuse large B-cell lymphoma: n = 2) who received crizotinib monotherapy." (PMID 35207754, 2022). "When administered to a small group of ALK-positive ALCL and ALK-positive diffuse large B-cell lymphoma RR patients, there was an ORR of 90.9% with 100% CR in the ALCL group." (PMID 32934797, 2020). "Anaplastic lymphoma kinase-positive large B-cell lymphoma (ALK+ LBCL) is a very rare and aggressive subtype of diffuse large B-cell lymphoma characterized by ALK rearrangement." (PMID 29992063, 2018). "Cytoplasmic ALK fusion proteins are present in tumors including NSCLC, ALCL, and diffuse large B-cell lymphoma." (PMID 27732954, 2016). "Differential diagnostic considerations for PBM include lymphoid neoplasms with plasmablastic, immunoblastic, or plasmacytoid features, such as diffuse large B‐cell lymphoma (DLBCL), HHV‐8 DLBCL‐NOS, ALK‐positive large B‐cell lymphoma, primary effusion lymphoma, and plasmablastic lymphoma (PBL)." (PMID 39866923, 2025). "ALK+ ALCL is rare in adults (people over the age of 18), and it is especially rare in people over the age of 50, yet it is one of the most common pediatric lymphomas after Burkitt lymphoma, Burkitt-like lymphoma, lymphoblastic T-cell lymphomas, and diffuse large B-cell lymphoma." (PMID 37655119, 2023). "The second most common deletion was 6q21 (56% versus 6% in ALCL ALK− versus ALK+, respectively), resulting in deletion of the B cell differentiation factor BLIMP1, which is known to be disrupted in many cases of activated B cells, such as diffuse large B cell lymphoma." (PMID 25820993, 2015). "Another differential consideration is the intravascular dissemination of a mass-forming lymphoma, such as diffuse large B-cell lymphoma (DLBCL) or ALK-negative anaplastic large cell lymphoma." (PMID 40723240, 2025).
diffuse large B-cell lymphoma (continued). "Of all the B-NHL, there were 418 cases of DLBCL, accounting for the highest proportion (18.3%, 418/2291), including diffuse large B-cell lymphoma-not otherwise specified (DLBCL-NOS), primary mediastinal large B-cell lymphoma (PMBL), EBV-positive DLBCL and ALK-positive large B-cell lymphoma (LBCL)." (PMID 37182167, 2023).
glioma (61 papers, 2012 to 2026). A benign or malignant brain and spinal cord tumor that arises from glial cells (astrocytes, oligodendrocytes, ependymal cells). "The present comprehensive scoping review has provided an overview on the presence of ALK expression and of ALK genetic alterations in various non-glial tumors of the posterior cranial fossa, a site associated with increased surgical morbidity and mortality." (PMID 38339401, 2024). "In this scoping review, we will provide an overview of the evidence indicating diagnostic/prognostic value of ALK expression and of ALK genetic/molecular alterations in primary CNS, non-glial tumors presenting in the posterior cranial fossa." (PMID 38339401, 2024). "A rare subset of pediatric gliomas - infant-type hemispheric gliomas (IHG) - are driven by oncogenic fusions involving the receptor tyrosine kinase (RTK)-encoding genes ALK, ROS1, MET, and the NTRK-family." (PMID 37781183, 2023). "Pair-wise comparison of CNAs in the glioma-associated genes ALK, PDGFRA, VEGFR2/KDR, EGFR, MET and FGFR1 was performed employing MLPA techniques." (PMID 30894200, 2019). "In contrast, published data related to glial tumors suggest that the role of activating ALK fusions or mutations in the development of most primary central nervous system (CNS) tumors is minimal, with the exception of the extremely rare cases of infant-type hemispheric gliomas." (PMID 38339401, 2024). "Mutations in genes including ROS1, ALK, NF1, KRAS, MEK, and CRAF have been identified across glioma subtypes, highlighting the necessity for molecular classification beyond traditional histopathology." (PMID 41514664, 2026). "A recent study has demonstrated that ctDNA from metastatic brain tumors, including mutations in ALK and MDM2, can be used to effectively differentiate metastatic brain tumors from gliomas." (PMID 41219968, 2025). "This compound is an anaplastic lymphoma kinase (ALK) inhibitor and has been associated with anti-tumor effects and increased chemosensitivity, including in glioma cells." (PMID 41007824, 2025). "Following the PRISMA-ScR guidelines, studies were included if they investigated ALK’s role in primary CNS, non-glial tumors located in the posterior cranial fossa." (PMID 38339401, 2024). "This review aims at mapping the available literature on the involvement of ALK in non-glial tumors localized in the posterior cranial fossa and at identifying diagnostic, prognostic, and therapeutic considerations." (PMID 38339401, 2024). "Lorlatinib, a third-generation ALK inhibitor, has shown a treatment advantage over chemotherapy in ALK-rearranged gliomas in mouse models." (PMID 39409964, 2024). "The Pediatric MATCH Screening Trial (NCT03155620) is currently recruiting children with recurrent solid malignancies, including high-grade gliomas with ALK alterations, to evaluate the effects of this novel drug." (PMID 38139220, 2023). "Pharmacological targeting of the MDK/ALK axis with crizotinib effectively acts on the population of glioma-initiating cells (GIC) in vitro and in tumor xenografts." (PMID 35625997, 2022). "Midkine (MDK), an anaplastic lymphoma kinase (ALK) ligand, also promotes the resistance of glioma cells to anticancer therapies such as radiotherapy (RT) and temozolomide (TMZ)." (PMID 35625997, 2022). "A potential mechanism involved in spontaneous differentiation of gliomas harboring ALK/ROS1/NTRK/MET alterations is oncogene-induced senescence." (PMID 34704035, 2021). "NTRK1-3, ROS1, and ALK fusion genes in infantile glioma are targetable, therefore, nationwide adaptation of NGS to evaluate these fusion genes and more extensive accumulation of clinical data are required." (PMID 33673070, 2021).